PNPLA3 (patatin like domain 3, 1-acylglycerol-3-phosphate O-acyltransferase )
Diseases named in the same sentence as PNPLA3 in open-access papers (continued):
Sharing a sentence is not in itself a finding about the gene and the disease.
Obesity (continued). "Several lines of evidence suggest that in patients with either T2DM or obesity (BMI >30 kg/m2), PNPLA3 is significantly upregulated by insulin resistance." (PMID 40677694, 2025). "We previously investigated this cohort for variants in the PNPLA3 and TM6SF2 genes to identify people at a higher risk of liver steatosis (PNPLA3) and fibrosis (TM6SF2), a condition frequently associated with obesity, diabetes, and metabolic syndrome." (PMID 38649714, 2024). "The prevalence of dyslipidemia and obesity in patients with MASLD wild-type for PNPLA3 was 67% for both metabolic variables." (PMID 39728506, 2024). "Obesity also amplifies the interaction of PNPLA3 I148M with alanine transaminase ALT level and cirrhosis." (PMID 37361533, 2023). "To this end, we examined hepatic PNPLA3 expression in the transcriptomic cohort (n = 125) of individuals with obesity stratified by sex and PNPLA3 genotype." (PMID 37749332, 2023). "In individuals with obesity, hepatic PNPLA3 expression was higher in women than in men (P = 0.007) and in mice correlated with estrogen levels." (PMID 37749332, 2023). "PNPLA3 I148M has a more severe effect on liver injury in people with obesity than in lean individuals." (PMID 37361533, 2023). "NAFLD predominantly manifests in patients with obesity, insulin resistance, and dyslipidemia, although genetic factors, such as Patatin-like phospholipase domain-containing protein 3 (PNPLA3), play a role." (PMID 35883775, 2022). "Specifically, the most well-described variants are patatin-like phospholipase domain-containing protein 3 (PNPLA3) I148M, transmembrane 6 superfamily member 2 (TM6SF2) E167K and obesity-linked suppression of membrane-bound O-acyltransferase 7 (MBOAT7)." (PMID 34977507, 2022). "Our study only recruited individuals with overweight and obesity and this undermined our ability to evaluate interactions between PNPLA3 genotype status and dietary intake in normal weight individuals." (PMID 34280991, 2021). "For example, the coexistence of severe obesity was found to strongly influence the impact of PNPLA3 I148M on systemic insulin sensitivity." (PMID 33102799, 2020). "In fact, among the targets responsive to thyroid hormones and involved in obesity, Pnpla3 plays a role in the enlargement of eWAT35." (PMID 32704052, 2020). "In addition to the effect on liver, PNPLA3 rs738409 variant has been reported to be associate with reduced glomerular filtration rate (GFR) in children with obesity, indicating the variant PNPLA3 genotype may be related to kidney dysfunction in children independent of MAFLD status." (PMID 33363067, 2020). "Because NAFLD is closely linked to obesity, we also explored the specific SNP × SNP interaction of the major obesity locus, FTO (rs1421085) and PNPLA3 (rs738409)." (PMID 31311600, 2019). "As evaluated by BMI, both HS and CHB+HS patients carrying CC and TC genotype of PNPLA3 rs1010023 showed much less sensitive to obesity in comparison to those with TT genotype." (PMID 28695131, 2017). "Genes with smaller betweenness centrality play important adipose specific functions as well; for example, gene expression levels of PNPLA3 are affected by diet-induced obesity, and LGPAT1 was shown to influence BMI and percent body fat in Native Americans." (PMID 27467526, 2016). "On the other hand, previous reports have shown that obesity is one of the triggers of liver damage in the carriers of the PNPLA3 G/G genotype." (PMID 26200108, 2015). "On the other hand, data concordantly indicate that the PNPLA3 148M predisposes to HCC in ALD, and is a risk factor for HCC in obesity." (PMID 24155878, 2013). "Carotid plaques, IMT thickening and mean maximum IMT were similar in the two cohorts, whereas the prevalence of diabetes, obesity, NASH, and PNPLA3 GG polymorphism(21%vs.13%, p = 0.02) were significantly higher in the Sicilian cohort." (PMID 24069270, 2013).
Obesity (continued). "Apart from the PNPLA3 gene, many other genes can also influence the development of obesity and NAFLD via affecting lipid metabolism, cytokines, fibrosis mediators and oxidative stress." (PMID 22978800, 2012). "We did find a modest effect of PNPLA1 on obesity and PNPLA3 on insulin sensitivity although these data need confirmatory studies." (PMID 19390624, 2009). "Obesity-associated variants in PNPLA1 and PNPLA3 and the association with phenotypes using multiple regression analyses." (PMID 19390624, 2009). "Conversely, the rs6006460[T] variant in PNPLA3, which encodes the S453I substitution, is linked to reduced hepatic fat content in African Americans, potentially explaining their lower risk of SLD despite similar rates of obesity and insulin resistance." (PMID 41466424, 2025). "However, changes in HDL subfractions were more pronounced in PNPLA3 GG patients with obesity than in those with T2DM." (PMID 40677694, 2025). "Notably, PNPLA3 GG carriers with diabetes and obesity had significantly lower VLDL-1 lipids even in the fasted state compared with CC carriers, highlighting the impact of the PNPLA3 rs738409 (p.I148M) variant in these patients at high metabolic risk." (PMID 40677694, 2025). "In addition, obesity interacts with PNPLA3 I148M genetic variation to elevate liver fat content and NAFLD susceptibility, and to increase the risk of liver injury, liver fibrosis and HCC." (PMID 37361533, 2023). "Alternatively, FASN is a crucial liver enzyme for lipid homeostasis and triglyceride synthesis, and PNPLA3 is a marker that is pathologically characterized by the regulation of lipogenesis in obesity, nonalcoholic fatty liver disease, and cardiovascular disease." (PMID 34564583, 2021). "PNPLA3 increases the fatty load of the liver but was not yet proved to cause insulin resistance.The majority of patients with diabetes and obesity have ab initio insulinresistance and significant cardio-metabolic risk." (PMID 34833467, 2021). "Fatty acid synthase (FASN) is a crucial liver enzyme for lipid homeostasis and triglyceride synthesis, whereas patatin-like phospholipid domain containing protein 3 (PNPLA3) is a pathologic marker for lipogenesis regulation in obesity, nonalcoholic fatty liver disease, and cardiovascular disease." (PMID 33401717, 2021). "The result showed that the protection of HSD17B13 rs72613567 on NASH and fibrosis might be limited to specific individuals who were aged ≥45 years, women who had class ≥2 obesity or diabetes, and those with PNPLA3 rs738409 CC genotype." (PMID 35071330, 2021). "Risk factors of rapid fibrosis progression in NAFLD includes the existence of NASH, age, severe obesity, high fructose consumption, insulin resistance, presence of T2D, high HbA1c levels, menopause in women, high ALT levels, and PNPLA3 G allele." (PMID 32570776, 2020). "Specifically, previous studies have found that SNPs within Cdh23 were correlated with BMI, SNPs in Tph2 were correlated with obesity, SNPs in Prox1 were correlated with glucose metabolism, SNPs in Lipc were correlated with cholesterol, and SNPs in Pnpla3 were correlated with hepatic lipid content." (PMID 31262088, 2019). "Therefore, current evidence suggests that the PNPLA3 I148M variant is a genetic determinant of liver damage progression associated with steatohepatitis, which may be triggered by a number of factors including obesity, IR, excessive alcohol intake, and chronic hepatitis C." (PMID 23394097, 2013). "It is intriguing to investigate whether metabolic comorbidities such as obesity and insulin resistance, which are associated with the pathogenesis of NAFLD, are also influenced by the PNPLA3 I148M variant." (PMID 23176674, 2012). "However, a recent study showed that hepatic Pnpla3 overexpression leads to changes in the glucose and triglycerides homeostasis in mouse models of obesity and diabetes." (PMID 22724004, 2012). "The expression level of PNPLA3 is nutritionally regulated, and increases with obesity." (PMID 23226254, 2012).
Obesity (continued). "Three variants in PNPLA3 showed association with obesity before, but not after, adjustment for age and gender (rs139051, rs12483959, and rs2072907, p>0.05)." (PMID 19390624, 2009). "PNPLA1 exhibited a modest effect on obesity and PNPLA3 on insulin sensitivity." (PMID 19390624, 2009). "The results suggest that PNPLA3 G-allele carriers of non-fatty liver develop liver fat and fibrosis due to not only obesity and insulin resistance but also the deterioration of gut microbiota, which may require a relatively long course of time, even years." (PMID 40074353, 2025). "PNPLA3 has an effect on triglyceride entrapment in lipid droplets of hepatocytes and stellate cells, but surprisingly does not have a significant association with obesity, diabetes, or serum lipids." (PMID 39142818, 2024). "The I148M PNPLA3 variant, the strongest genetic predictor of NAFLD onset and progression, may undergo nutritional regulation and its deleterious effect could be worsened by environmental factors as obesity." (PMID 36937355, 2023). "The association between the PNPLA3 G allele and liver fat contact in the non-obese population is significant because it is independent of insulin resistance and other metabolic comorbidities such as obesity and dyslipidemia." (PMID 36237544, 2022). "Although the mechanisms by which PNPLA3 polymorphism links to HCC has not completely known, it is anticipated that this genetic variant might promote hepatocarcinogenesis via metabolic disorders including obesity, diabetes, and steatohepatitis." (PMID 35696400, 2022). "Furthermore, apart from the well-known association between the rs738409 polymorphism in the PNPLA3 gene and NAFDL, we have also investigated the association of the polymorphism with atherosclerosis risk factors, such as overweight/obesity, abnormal lipid profile, and high blood pressure." (PMID 36079710, 2022). "Self-reported alcohol intake (nonexcessive vs excessive), obesity (body mass index ≥30 [calculated as weight in kilograms divided by height in meters squared]), and PNPLA3 I148M variant status (noncarrier, heterozygous carrier, or homozygous carrier) from initial assessment." (PMID 36190732, 2022). "Notably, HS associated with the PNPLA3 G allele is not necessarily characterized by features of MS, which is ultimately distinct from obesity-related HS." (PMID 30189691, 2018). "The PNPLA3 I148M variant may determine triglyceride profiles independent of obesity, supporting the idea that the I148M variant hampers intrahepatocellular lipolysis rather than stimulates triglyceride synthesis." (PMID 25411786, 2014). "The gene/obesity interaction, where the association is only seen in a fairly extreme subgroup, may explain why the PNPLA3 148M allele has not been widely associated with serum triglyceride levels, insulin resistance and type 2 diabetes in other studies." (PMID 22724004, 2012). "We could not find any significant associations between the PNPLA3 I148M polymorphism and serum levels of liver enzymes or markers of the metabolic syndrome (obesity, diabetes mellitus or serum lipids) (data not shown)." (PMID 22087248, 2011). "For obesity, the model yielded an AUROC of 0.35, and for Type 2 diabetes, an AUROC of 0.47—both values substantially lower than the AUROC of 0.68 observed for PNPLA3 I148M homozygosity." (PMID 40478199, 2025). "Consistent with this, we demonstrated a better separation of the metabolome between PNPLA3 GG and CC carriers in patients with T2DM and obesity compared with the total cohort." (PMID 40677694, 2025). "NAFLD is driven by multiple factors, including lifestyle, genetics (i.e., Patatin-like phospholipase domain-containing protein 3, PNPLA3) and other metabolic conditions, such as Type 2 Diabetes (T2D) and obesity." (PMID 35421611, 2022). "The effects of TM6SF2, PNPLA3 and glucokinase gene regulator on NAFLD are additive in some individuals and can be augmented by obesity." (PMID 32776921, 2020).
Obesity (continued). "•Metabolic alterations increase in PNPLA3 GG carriers with T2DM and/or obesity." (PMID 40677694, 2025). "Although PNPLA3 GG carriers showed a trend toward lower BMI and less frequent obesity compared with non-carriers, these differences remained without statistical significance." (PMID 40677694, 2025). "Notably, the Authors found a positive interaction between the PNPLA3‐rs738409‐GG and metabolic disorders like T2DM and obesity." (PMID 39412170, 2025). "PNPLA3 has been proved to play a significant role in determining the fatty hepatic load independent of obesity." (PMID 34833467, 2021). "In previous studies, the PNPLA3 SNP did not play any role in obesity, insulin resistance, or incidence of T2D." (PMID 32570776, 2020). "Obesity-related NAFLD patients exhibit the same distribution of PNPLA3 genotype as non-obese patients, whereas inflammation-related genes are upregulated in adipose tissue." (PMID 24786095, 2014). "On the contrary, these levels are not influenced by global obesity, MetS, CRP, HOMA-IR, ALT or by genomic variants related to PNPLA3, chronic inflammation, and oxidative stress in the overall population." (PMID 23935829, 2013). "We found borderline association with obesity for PNPLA1 and PNPLA3, but these data would not hold for multiple corrections." (PMID 19390624, 2009). "The most common predisposing factors for NAFLD are male sex, age > 50 years, hyperlipidemia, obesity, insulin resistance and T2DM, and a lack of physical exercise as well as genetic polymorphisms (e.g., patatin-like phospholipase domain-containing 3 (PNPLA3) I148M polymorphism)." (PMID 36010588, 2022). "Additionally, adipose PNPLA3 mRNA expression in mice with genetic-induced obesity and diet-induced obesity appeared to no longer respond to carbohydrate refeeding." (PMID 33531537, 2021). "However, PNPLA3-related NASH could be seen in lean patients; thus, obesity-related visceral fat accumulation can partially explain NAFLD pathogenesis." (PMID 24786095, 2014). "Interestingly, clinical epidemiological data shows that even if metabolic abnormalities like obesity, dyslipidemia or T2DM are absent, NAFLD may be seen in the subjects with variant PNPLA3." (PMID 31399032, 2019). "The PNPLA3-related NAFLD was characterized by absolute and relative deficiencies of circulating triacylglycerols compared to obesity-related NAFLD, thus suggesting that the PNPLA3 polymorphism may impair lipolysis rather than stimulate the synthesis of intrahepatocellular triacylglycerols." (PMID 26200108, 2015). "Twenty percent of Japanese NAFLD patients have NAFLD without obesity (i.e., lean NAFLD), and the involvement of the patatin-like phospholipase domain-containing 3 protein (PNPLA3) gene has been reported." (PMID 38004118, 2023).
non-alcoholic fatty liver disease (110 papers, 2010 to 2026). "Individuals carrying risk alleles in PNPLA3, a gene associated with non-alcoholic fatty liver disease, appear particularly responsive to fermented food interventions, suggesting gene–diet interactions in epigenetic outcomes." (PMID 41596220, 2026). "The patatin-like phospholipase domain containing 3 (PNPLA3) gene is associated with the development of nonalcoholic fatty liver disease, and the high-risk allele is found more commonly in the Mexican indigenous population." (PMID 40771231, 2025). "The SNP rs738408 on PNPLA3 is a synonymous variant that has been associated with Non-Alcoholic Fatty Liver Disease." (PMID 40892850, 2025). "The rs738409 variant (I148M) of the Patatin-like phosphatase domain-containing 3 (PNPLA3) gene is the most common gene associated with non-alcoholic fatty liver disease (NAFLD), a condition contributed by genetic factors in one-third of individuals." (PMID 38257154, 2024). "Patatin-like phospholipase domain-containing 3 (PNPLA3) is a major susceptibility gene for nonalcoholic fatty liver disease (NAFLD), and its rs738409 (I148M) polymorphism is associated with the occurrence and progression of NAFLD." (PMID 36825197, 2023). "Genetic variation in the gene patatin-like phospholipase domain-containing protein 3 (PNPLA3) confers susceptibility to nonalcoholic fatty liver disease." (PMID 38027204, 2023). "This is interesting, because Pnpla3 is required for HSC activation and a genetic variant of PNPLA3 predisposes for development of non-alcoholic fatty liver disease (NAFLD), the pathogenesis of which includes HSC activation." (PMID 36997988, 2023). "Nonalcoholic fatty liver disease (NAFLD) showed significant association with PNPLA3 rs738409 polymorphism in unrelated individuals." (PMID 35486295, 2022). "Patatin-like phospholipase domain containing 3 (PNPLA3) is the main nonalcoholic fatty liver disease (NAFLD) susceptibility." (PMID 35624499, 2022). "Diet, physical activity, and the PNPLA3 gene are known risk factors for non-alcoholic fatty liver disease (NAFLD)." (PMID 35276911, 2022). "PNPLA3 is a lipase, involved in the hydrolysis of triacylglycerol molecules in adipocytes and considered a risk factor for non-alcoholic fatty liver disease (NAFLD) and HCC." (PMID 35159342, 2022). "Patatin-like phospholipase domain-containing 3 (PNPLA3) is a lipase of interest in human medical research because of a genetic mutation (rs738409) associated with nonalcoholic fatty liver disease (NAFLD) and steatohepatitis." (PMID 33531537, 2021). "A genetic variant (rs738409) of PNPLA3 was associated with non-alcoholic fatty liver disease (NAFLD) and its histological severity in GWAS." (PMID 33594477, 2021). "In T2DM women, the PNPLA3 rs738409 polymorphism, a genetic risk factor for non-alcoholic fatty liver disease, was associated with impaired eGFR values and DKD prevalence, irrespective of the presence of NAFLD and common cardio–renal risk factors." (PMID 34071671, 2021). "This variant mapped to the nearby gene PNPLA3, a well-established locus associated for non-alcoholic fatty liver disease, multiple liver enzymes measures, hemotological traits, sex-hormone binding globulin levels, and T2D." (PMID 35186008, 2021). "PNPLA3 is closely involved with lipid metabolism and is a risk factor for non-alcoholic fatty liver disease (NAFLD) and hepatocellular cancer (HCC)." (PMID 33669694, 2021). "The relationship between rs738409, a nonsynonymous variant (p.Ile148Met) in the PNPLA3 gene, and non-alcoholic fatty liver disease (NAFLD) has been well established." (PMID 34503513, 2021). "This study investigated the association between PNPLA3 I148M rs738409 polymorphism and non-alcoholic fatty liver disease through systematic review and meta-analysis." (PMID 34147109, 2021).